CRP (C-reactive protein)
Diseases named in the same sentence as CRP in open-access papers (continued):
Sharing a sentence is not in itself a finding about the gene and the disease.
oral squamous cell carcinoma (15 papers, 2010 to 2025). "Squamous cell carcinoma antigen (SCC-Ag) and C-reactive protein (CRP) levels have been successfully used to stratify risk groups in primary oral squamous cell carcinoma (OSCC) patients; however, related biomarkers have rarely been investigated in recurrent OSCC." (PMID 25061977, 2014). "A study by Gosavi and Torkadi compared the serum CRP levels of 150 study participants including 50 with oral submucous fibrosis, 50 with oral squamous cell carcinoma and 50 normal controls." (PMID 39851610, 2025). "We evaluated factors that influence the preoperative CRP/alb ratio in oral squamous cell carcinoma (OSCC) patients and in particular clarified the role of oral health to this ratio." (PMID 33740951, 2021). "We previously demonstrated that CRP was an independent prognostic factor in oral cavity squamous cell carcinoma (OSCC)." (PMID 28209200, 2017). "Preoperative serum CRP level was a prognosticator in oral squamous cell carcinoma, and its effect was more prominent in buccal cancer that occurs more frequently in areca-quid (AQ) endemic regions." (PMID 28209200, 2017). "The combined roles of CYFRA 21-1 and CRP levels were rarely investigated in oral squamous cell carcinoma (OSCC)." (PMID 26292957, 2015). "Although the role of CRP in oral cavity SCC is controversial, studies have recently demonstrated the prognostic value of CRP in OSCC." (PMID 25061977, 2014). "Reports from the study of oral cavity SCC have suggested a relationship between CRP level and poor outcomes, pathological tumor status, nodal status and lymph node ECS." (PMID 23383155, 2013). "Similarly to previous study, elevated CRP/ALB ratio was observed in oral squamous cell carcinoma patients with poor overall survival." (PMID 35982996, 2022). "In further studies, CRP levels in precancerous lesions and in Human Papilloma Virus (HPV) positive patients with oral squamous cell carcinoma (SCC) should be studied." (PMID 20673375, 2010). "Although the C-reactive protein-to-albumin ratio (CAR) can predict poor outcomes in assorted cancers, its prognostic value in oral cavity squamous cell carcinoma (OSCC) remains unclear." (PMID 32587804, 2020).
Pruritus (15 papers, 2012 to 2025). Pruritus is an itch or a sensation that makes a person want to scratch. "A correlational study showed that the severity of pruritus was significantly associated with skin moisture and serum CRP." (PMID 39139799, 2024). "The significantly positive correlation between serum CRP and pruritus score indicates that systemic inflammation is involved in eliciting pruritus." (PMID 39139799, 2024). "In MF patients, those with pruritus displayed significantly higher CRP, NLR, mSWAT and DLQI scores compared to those without pruritus (p = 0.031, p = 0.048, p = 0.040 and p < 0.001, respectively)." (PMID 38332520, 2024). "In the present study, we found that supplementation with omega-3 PUFA significantly decreased both the plasma CRP and IL-6 levels, as well as the consequent severity of pruritus in hemodialysis patients." (PMID 35744059, 2022). "In an international prospective cohort study on HD patients, the patients with pruritus were older, had higher median C-reactive protein, and had hepatitis B or C antibodies and low serum albumin." (PMID 34437400, 2021). "Additionally, rather than OSA being a correlate for pruritus, it has been reported that patients with pruritus had higher CRP levels, which serves as a biomarker for disease activity in OSA." (PMID 40572681, 2025). "Serum CRP was positively correlated with pruritus levels at baseline and the 3rd month." (PMID 39139799, 2024). "The common diagnostic tests included complete blood count, liver function, renal function test, congenital pruritus C1 esterase deficiency, serum immunoglobulin, antinuclear antibody (ANA), thyroid test, C-reactive protein test and immunoglobulin E (Ig E) levels." (PMID 35076499, 2022). "This hypothesis was supported by the elevated serum levels of the C-reactive protein (CRP) and the inflammatory cytokines interleukin (IL)-2 and IL-6 in HD patients with pruritus versus those free from pruritus." (PMID 35324695, 2022). "Additionally, pruritus exhibited a mild correlation with CRP, NLR, MLR and SIRI." (PMID 38332520, 2024). "Pruritus exhibited correlations with DLQI, mSWAT, CRP, NLR, MLR and SIRI (r = 0.607, p < 0.001; r = 0.235, p = 0.035; r = 0.270, p = 0.036; r = 0.276, p = 0.013; r = 0.221, p = 0.047 and r = 0.267, p = 0.016, respectively)." (PMID 38332520, 2024). "Patients with UP showed significantly higher age, dialysis duration, hemoglobin, phosphorus, uric acid, intact PTH, hs-CRP, magnesium, and triglyceride levels compared to those without pruritus." (PMID 40666577, 2025). "Pruritus was positively correlated with DLQI, mSWAT, CRP, NLR, MLR and SIRI." (PMID 38332520, 2024). "(iii) Pruritus was significantly correlated with DLQI, mSWAT, CRP, NLR, MLR and SIRI." (PMID 38332520, 2024). "Supplementation with MT did not significantly affect pruritus score, sleep fragmentation, mobility in sleep, total sleep time and CRP value in both studies." (PMID 34439427, 2021). "In our study, the OR value for hs-CRP of patients with severe skin itching was significantly higher than that of patients without itching, suggesting that higher hs-CRP levels were closely associated with severe skin itching, which was consistent with the results of an earlier study." (PMID 33471852, 2021). "Compared with patients without itching, the OR value for mild skin itching was 1.740, that for moderate skin itching was 2.838, and that for severe skin itching was 9.440, indicating that degree of skin itching increased along with hs-CRP levels." (PMID 33471852, 2021). "First, patients undergoing hemodialysis who develop pruritus with no obvious visible signs of inflammation have significantly higher serum levels of C-reactive protein, IL-6, IFN-γ, IL-2, and IL-31 than patients without pruritus." (PMID 40596915, 2025). "CRP, NLR, mSWAT and DLQI score were significantly higher in MF patients with pruritus than those without." (PMID 38332520, 2024).
Pruritus (continued). "(ii) Among MF patients, those with pruritus showed significantly elevated levels of CRP, NLR, mSWAT and DLQI scores compared to those without pruritus." (PMID 38332520, 2024).
Respiratory insufficiency (15 papers, 2006 to 2025). "A study concluded that elevated CRP levels are highly and independently linked to respiratory impairment and more frequent Bronchial Hyperresponsiveness (BHR), and these results indicate that both respiratory impairment and BHR are related to a systemic inflammatory process." (PMID 37873776, 2023). "At COVID-19 disease day 11 he was admitted to the hospital, because of respiratory insufficiency requiring additional oxygen suppletion, and with a CRP level of 249.9 mg/L." (PMID 35651879, 2022). "Levels of CgA were independent predictors of in-hospital mortality (hazard ratio 1.28 [95% confidence interval 1.077–1.522], p = 0.005) when adjusted for age, number of comorbidities, respiratory insufficiency degree, C-reactive protein levels and time from symptom onset to sampling." (PMID 35468164, 2022). "Against the background of progressively increasing respiratory insufficiency, the patient was transferred to high-flow oxygenation from 20 to 65 L/min, CRP increased to 52.4 mg/L; due to the deterioration of the condition, a transfer to artificial lung ventilation was planned." (PMID 36883180, 2022). "On the other hand, when focusing on day three respiratory insufficiency, the predictive values of the SIRS components, the CRP concentration, the PaO2/FIO2 ratio and the MODS score were poor." (PMID 16859526, 2006).
viral meningitis (15 papers, 2012 to 2025). Inflammation of the membranes surrounding the brain and spinal cord due to a viral infection. "A 2024 systematic review on the accuracy of CSF biomarkers for the diagnosis of pediatric meningitis found a high diagnostic accuracy for CSF CRP, with a summarised AUC of 0.94 (95% CI: 0.92–0.97) for differentiating bacterial from viral meningitis." (PMID 40636058, 2025). "Three studies that included diagnostic performance characteristics for CRP to distinguish between bacterial and viral meningitis found similar sensitivities (73.3%-86%) and a wider range of specificities (78%-94%) to identify bacterial infections." (PMID 27486746, 2016). "However, all studies also presented data on other host biomarkers that performed with greater diagnostic accuracy than CRP in differentiating bacterial from viral meningitis." (PMID 27486746, 2016). "In contrast, patients with viral meningitis have a plasma protein profile dominated by acute-phase and pro-inflammatory markers (e.g., CRP, S100A8, S100A9) and immunoglobulin production." (PMID 41145505, 2025). "Comparison of serum WBC and CRP levels for patients with bacterial/viral meningitis showed that mean CRP level was significantly higher among those with bacterial infection than viral (4.41 vs 3.29, 2-sample t-test, p < 0.0001)." (PMID 41510242, 2025). "In viral meningitis, CSF protein significantly correlated with WBCs (r = 0.353, P = 0.041) and CSF glucose levels correlated with CRP (r = 0.550, P = 0.001)." (PMID 34115780, 2021). "Notably, viral meningitis exhibited a different pattern, with both plasma and CSF showing elevated acute-phase reactants (e.g., CRP, S100A9) and immunoglobulins, consistent with a strong inflammatory and humoral response." (PMID 41145505, 2025). "In addition, PCT had higher performance in discriminating bacterial form viral meningitis compared to WBCs and CRP (AUC = 0.951) and at a cut-off value of 0.98 ng/ml, with sensitivity and NPV of 100%." (PMID 34115780, 2021). "Unlike previous studies, we found that serum CRP had poor diagnostic performance to discriminate bacterial from viral meningitis." (PMID 34115780, 2021). "There are some inflammatory mediators in CSF or serum that help to differential diagnosis of bacterial and viral meningitis such as IL6, CRP, Pre- calcitonin, TNF, IL8." (PMID 23483792, 2012). "The meta-analysis showed that, although the majority of authors propose using CRP as an additional tool for discriminating bacterial from viral meningitis, only negative CRP tests are highly informative in most clinical settings." (PMID 29891780, 2018). "Two old retrospective studies reported high sensitivities and negative predictive values for CRP in differentiating bacterial from viral meningitis and other central nervous system infections." (PMID 22943554, 2012).
aortic valve stenosis (14 papers, 2006 to 2025). Aortic valve stenosis (AVS) is a condition characterized by narrowing of the heart's aortic valve opening. "Demographic, clinical and laboratory characteristics of 300 aortic valve stenosis patients with regard to the C-reactive protein (CRP) gene rs1205 C>T polymorphism." (PMID 26473826, 2015). "Our analysis identified CRP, PCT, and JMJD3 as independent factors associated with post-NEC intestinal stenosis." (PMID 40801194, 2025). "We also found signs of systemic involvement in patients with aortic valve stenosis, as indicated by higher levels of C-reactive protein." (PMID 38252146, 2024). "The expression of SIRT1 protein, which inhibits inflammatory response, was low in NEC secondary intestinal stricture and was negatively correlated with CRP expression." (PMID 35958178, 2022). "Elevation in C-reactive protein (CRP) levels have been shown in patients with aortic valve stenosis (AS)." (PMID 26473826, 2015). "In conclusion, CRP, PCT and JMJD3 are significantly upregulated in NEC children with intestinal stenosis, and serve as key risk factors associated with the development of post-NEC intestinal stenosis." (PMID 40801194, 2025). "The persistent elevation of CRP and abnormal lactate levels have been identified as predictors of post-NEC intestinal stenosis, which supports our findings." (PMID 40801194, 2025). "We also revealed subclavian stenosis, vascular bruit, erythrocyte sedimentation rate (ESR), and C-reactive protein (CRP) elevation; therefore, a diagnosis of TA was made." (PMID 33425551, 2020). "However, the post-NEC intestinal stenosis group demonstrated a significant decrease in PLT levels, alongside significant elevations in serum concentrations of CRP, PCT and JMJD3 expression in intestinal tissues when compared to the NEC group (P < 0.05)." (PMID 40801194, 2025). "In 8 infants, no increase in CRP levels was seen; none of these infants presented with secondary intestinal stricture." (PMID 24146936, 2013). "Other limitations include a lack of objective measures of stricture improvement, and although laboratory markers such as CRP, ESR, and albumin were measured, changes in these measures were not specifically reported for the stricture group." (PMID 36895272, 2023).
chronic bronchitis (14 papers, 2015 to 2025). A type of chronic obstructive pulmonary disease characterized by chronic inflammation in the bronchial tree that results in edema, mucus production, obstruction, and reduced airflow to and from the lung alveoli. "In rats with chronic bronchitis induced by MBS concentrations of selected factors VEGF, TGF-β1, TGF-β2, TGF-β3, MUC5AC, and CRP were determined using appropriate ELISA methods." (PMID 33138217, 2020). "In this study, we focused on the effects of the extracts from PG on the concentrations of a few factors possibly involved in pathogenesis of chronic bronchitis (VEGF, TGF-β1, TGF-β2, TGF-β3, MUC5AC, and CRP)." (PMID 33138217, 2020). "In the other model 4, (corresponding to model 2 but also adjusted for preoperative CRP levels), the independent factors were: FEV1% class (p = 0.000018), GOLD category (p = 0.0025), chronic bronchitis (p = 0.012), age (0.0075), stage of disease (p = 0.019), and CRP levels (p = 0.037)." (PMID 35205621, 2022). "The independents factors were: age (p = 0.006), CRP levels (p = 0.041), stage of disease (p = 0.045), cumulative smoking (p = 0.048), and BMI class (p = 0.044) while chronic bronchitis also showed a strong, but not statistically significant, trend (p = 0.076)." (PMID 35205621, 2022).
cystitis (14 papers, 2013 to 2025). Inflammation of the urinary bladder. "CRP ≥55 mg/l or 80 mg/l give a LR+ of 3.56 (95% CI 2.02–5.12, n = 9) and 4.38 (95% CI 2.02–5.13, n = 9) for cystitis." (PMID 34565335, 2021). "Manual removal of the placenta (p<0.001), fever (p<0.001), endomyometritis (p= 0.024), wound infection (p=0.031) and cystitis (p=0.024) resulted in higher CRP level." (PMID 32082531, 2019). "In a study done by KW Seo, JB Lee, JO Ahn, HW Lee, CY Hwang, HY Youn and CW Lee, dogs with experimentally induced cystitis showed higher CRP values in serum than the control group." (PMID 26746899, 2016). "In dogs, CRP in serum can be used as an indicator of inflammatory response to experimentally induced cystitis." (PMID 26746899, 2016). "The LR+ of CRP for cystitis varied between the primary studies." (PMID 34565335, 2021). "Our results, therefore, support the hypothesis that serum CRP levels can serve as an adjunct diagnostic tool for UTIs but still seems to be not sufficient for distinguishing between inflammation and cystitis properly." (PMID 40142190, 2025). "The median serum CRP level in this cohort was 26 mg/L (IQR: 15–38), and the mean serum procalcitonin level was 0.31 ng/mL (±0.32), supporting presence of cystitis." (PMID 40142190, 2025). "This was indicated by significantly higher levels of C-reactive protein (CRP) and a significant reduction in antibiotics only used for less severe infections, such as cystitis, during the intervention." (PMID 27464508, 2016). "In a population with very low infectious postpartum complications we were not able to use CRP to predict endomyometritis, cystitis or wound infection." (PMID 32082531, 2019). "Urine samples with bacteria and/or leukocytes had no significant increase in urinary NGF (p = 0.1112) or CRP (p = 0.0534) concentrations, but higher CRP-levels in urine from dogs with cystitis were found compared to dogs without signs of cystitis." (PMID 26746899, 2016). "In the meta-analysis, CRP and PCT have low accuracy for cystitis, but might be useful for PN." (PMID 37920790, 2023). "Additionally, CRP/Crea levels in dogs suffering from spinal cord disorders with micturition dysfunction with cystitis were higher than in dogs without cystitis." (PMID 26746899, 2016). "CRP/Crea and NGF/Crea values of dogs with cystitis were higher than in dogs without bacteria and/or leukocytes in the urine." (PMID 26746899, 2016).
Erythema nodosum (14 papers, 2013 to 2025). An erythematous eruption commonly associated with drug reactions or infection and characterized by inflammatory nodules that are usually tender, multiple, and bilateral. "Other studies have suggested that elevated levels of ESR and CRP are associated with newly-formed erythema nodosum, superficial thrombophlebitis, and articular involvement." (PMID 37223587, 2023). "While CRP was found to be high in erythema nodosum and vascular symptoms in one study, it was found to be high especially in vascular involvement in another study." (PMID 39050391, 2024). "Two years later, she was hospitalized for fever, anorexia, lymph node tenderness, and erythema nodosum with significant increases in CRP and sIL-2R." (PMID 40729186, 2023). "Over the next year, the patient continued to depend on prednisone doses ≥ 10 mg daily to control breakthrough fevers and erythema nodosum, and associated increases in his already elevated ESR and CRP." (PMID 37430338, 2023). "On studying the immune pattern in cases of leprosy infection, Foss found an increase in TNF-α production associated with high levels of C-reactive protein, suggesting that TNF-α was involved in the inflammatory reaction of erythema nodosum." (PMID 26339136, 2015). "The first 347 patients with SLE, 382 patients with RA and 66 patients with erythema nodosum were selected for the measurement of complement and CRP levels in the serum, the erythema nodosum patients were the control group." (PMID 24223657, 2013). "A Japanese girl exhibited persistent fever with an increased white blood cell (WBC) count, elevated serum C-reactive protein (CRP) levels, skin manifestations (i.e., aseptic pustulosis and erythema nodosum), and physical developmental delay (and Clinical description)." (PMID 38652464, 2024). "We confirmed that ocular BS was more prevalent in male patients and more likely to have erythema nodosum and vascular involvement, while intestinal BS tends to have fever and hematologic involvement accompanied with elevated inflammation markers including ESR, CRP, SAA, and IL-6." (PMID 35488313, 2022).